GSK3B (glycogen synthase kinase 3 beta)
Diseases named in the same sentence as GSK3B in open-access papers (continued):
Sharing a sentence is not in itself a finding about the gene and the disease.
Anxiety (43 papers, 2009 to 2026). Intense feelings of nervousness, tension, or panic often arise in response to interpersonal stresses. "For example, heterozygous GSK3β-knockout mice showed altered sociability and anxiety levels, paralleling the changes associated with chronic lithium administration, which activates Wnt/β-catenin signaling." (PMID 37524878, 2023). "In contrast to GSK3β nulls, heterozygous mice survive but display anxiety and deficient memory reconsolidation." (PMID 35782378, 2022). "Removal of only one GSK-3β allele causes behavioral abnormalities, including aggressive behaviors, increased anxiety, and memory deficits, in GSK-3β heterozygous (+/-) mice." (PMID 31191636, 2019). "The modulation of neuronal activity by Gsk3β and Fxr1 in the mPFC is most probably linked to their effects on anxiety-related behaviors." (PMID 29706865, 2018). "Gsk3b+/- mice display multiple behavioral abnormalities, including reduced exploratory activity, increased anxiety-associated behaviors, and reduced aggressive behavior." (PMID 29234272, 2017). "Studies in GSK-3β+/- mice have shown increased anxiety-associated behavior, which is similar to our findings in GSK-3α KO females." (PMID 19925672, 2009). "If spending more time in a central place reflects anxiety also in birds, then it could be suggested that GSK-3β inhibition caused anxiety-like behavior in our experimental birds." (PMID 35574473, 2022). "In this study, we found that the postpartum anxiety and depressive symptoms, as well as the increased expression of hippocampal Sema3A and decreased phosphorylation of GSK3β caused by gestational stress could be reversed by systemic administration EGCG." (PMID 36776771, 2022). "The details of the mechanisms by which GAD67 in SOM neurons regulates Akt/GSK3β activity are still unclear, but impairment of Akt/GSK3β signaling may be associated with the development of an anxiety-like state in SOM-GAD67 mice." (PMID 31275123, 2019). "In addition, administration of the GSK3 inhibitor 4-benzyl-2-methyl-1,2,4-thiadiazolidine-3,5-dione (TDZD-8) or GSK3β haploinsufficiency rescue enhanced ‘anxiety’ and ‘behavioural despair’ phenotypes in 5-HT-deficient R439H tph2 knockin mice." (PMID 22826345, 2012). "Previous mouse genetic studies which decreased GSK3β levels found contradictory results on basal anxiety‐like responses." (PMID 40390305, 2025). "Ketamine ameliorated PTSD symptoms by reducing protein and gene expression levels of the GSK-3β pathway, thereby improving anxiety-like behaviour in SPS-exposed rats." (PMID 40097854, 2025). "In a mouse model of anxiety and sleep disruption, Hericium erinaceus mycelium induced an antidepressant-like effect modulating BDNF/TrkB/PI3K/Akt/GSK-3β pathways and ameliorated the rodent anxiety and sleep disturbance." (PMID 37592816, 2024). "For the GSK3β gene, a prior study found that rs334558 and rs6438552 are associated with MDD endophenotypes, which include symptoms of anxiety and P300 latency." (PMID 35126809, 2022). "Another “behavior” study reported that GSK-3β heterozygous mice exhibit reduced exploratory and anxiety behavior." (PMID 33572709, 2021). "Deletion of GSK3β in mPFC D2 neurons revealed its contribution to anxiety-related, cognitive, and social behaviors." (PMID 32584144, 2020). "GAD67 in SOM neurons regulates the anxiety-like state in mice mediated by the modification of cortical Akt/GSK3β activity." (PMID 31275123, 2019). "Mice with reduced Gsk3β or elevated Fxr1 expression in mPFC showed decreased anxiety-related behaviors and reduced AMPA mediated excitatory postsynaptic currents." (PMID 29706865, 2018). "This indicates that either selective increase in the expression of Fxr1 or knockout of Gsk3b in mPFC neurons is sufficient to reduce anxiety." (PMID 29706865, 2018). "We found that mice with GSK-3β deletion in DG excitatory neurons displayed spatial and fear memory defects with an anti-anxiety behavior." (PMID 28720858, 2017).
Anxiety (continued). "Taken together, we have observed that selective deletion of GSK-3β in DG excitatory neurons induces memory deficit and anxiety-like behavior with mechanisms involving impaired synaptic plasticity and neural inactivation." (PMID 28720858, 2017). "As hippocampal DG subset and GSK-3β are closely involved in anxiety, we also measured the anxiety behavior." (PMID 28720858, 2017). "We found that GSK-3β deletion in hippocampal DG excitatory neurons induced spatial and fear memory deficits with an anti-anxiety behavior." (PMID 28720858, 2017). "The overall effect of forebrain GSK3β depletion is a reduction in anxiety that is combined with an increase in the initiation of social interaction." (PMID 22826345, 2012). "Inhibition of GSK3β has been shown to replicate several effects of antidepressants in tests measuring behavioural despair or anxiety-like behaviours in rodents." (PMID 22826345, 2012). "A study reported that saffron administration to rats subjected to maternal social isolation from PND reversed memory impairments, reduced locomotor activity, pain sensitivity, and GSK-3β overexpression in adolescents, and partially improved anxiety and depression in adults." (PMID 41462633, 2025). "However, acute systemic GSK3β intervention decreased locomotor activity and induced anxiety-like behavior in the OFT." (PMID 36949769, 2023). "Further, miR-124 has been suggested to regulate glycogen synthase kinase 3β and glucocorticoid receptor levels in the context of AD (GSK3β and GR, respectively) and regulate anxiety as well as impulse control disorders that are indicative of poor decision-making in humans." (PMID 33676561, 2021). "We investigated whether GSK3β of mPFC D2 neurons is involved in the regulation of anxiety-related, cognitive, and social behaviors." (PMID 32584144, 2020). "Moreover, knockout of GSK3β in mPFC D2 neurons uncovered its involvement in the regulation of anxiety-related, cognitive, and social behaviors." (PMID 32584144, 2020). "Furthermore, treatment with a GSK3β inhibitor ameliorated stress-elicited anxiety-like behavior in mice." (PMID 31275123, 2019). "Thus, we evaluated anxiety-related behavioral outcomes after augmentation of Fxr1 and reduction of Gsk3β levels." (PMID 29706865, 2018). "Overall, results obtained using the DLET and OFT in mice with forebrain GSK3β deficiency are consistent with results obtained following a systemic inhibition of GSK3β, indicating a probable contribution of cortex and/or hippocampus CA1 GSK3β in the regulation of anxiety-related behaviours." (PMID 22826345, 2012). "This may partly explain the diverse effects of GSK3β in behaviors related to emotion, anxiety, and activity." (PMID 22912839, 2012). "In addition to the action on anxiety and depressive-like behaviour, the reduction of GSK3β activity also antagonizes the effects of a reduced 5-HT synthesis on social behaviour and aggression in mice expressing mutant TPH2." (PMID 22826345, 2012). "Given the effects observed on anxiety and social behaviour, we then explored whether forebrain GSK3β is also involved in resilience to social stress." (PMID 22826345, 2012). "Moreover, β-sitosterol could upregulate the resistance to lipid peroxidation and oxidative stress by means of estrogen receptor-mediated PI3K/AKT/GSK-3β signaling pathway in the dentate gyrus; this would have the function of relieving anxiety." (PMID 39410900, 2025). "Therefore, at this stage, without additional physiological measurements, we are aware that our single behavioral parameter is not sufficient to determine that inhibition of GSK3β causes anxiety in birds." (PMID 35574473, 2022). "Since activity of CUGBP1 is controlled by GSK3β, correction of GSK3β in CDM1 or DM1 models restores CUGBP1 activity and improves muscle (myotonia, weakness, atrophy, myopathy) and CNS (anxiety) phenotypes." (PMID 36142405, 2022).
Anxiety (continued). "To assess the link between Akt/GSK3β signaling and anxiety-like behavior in SOM-GAD67 mice, we examined the expression levels of Akt and GSK3β by Western blotting and calculated the expression ratio of phosphorylated forms/total proteins." (PMID 31275123, 2019). "Given the crosstalk reported for MAPK/ERK and AKT/GSK3β signaling pathways, it is therefore of interest to examine how SCOP regulates these anxiety-related signaling pathways in the BLA in vivo." (PMID 27640726, 2016). "It has been shown that the increase in GSK3β in DM1 affects the cyclin D3-CUGBP1 pathway, contributing to the DM1 muscle phenotype (myotonia, atrophy, muscle weakness and myopathy) in DM1 mice and muscle weakness, myopathy and anxiety in DMSXL mice." (PMID 36142405, 2022). "This indicates that a reduction of GSK3β expression in D2 neurons of the mPFC is sufficient to impact anxiety-related behaviors and does not affect locomotor behaviors." (PMID 32584144, 2020). "The mechanisms through which HFD might influence depression- and anxiety-like behaviors are not completely understood, but preclinical work has suggested a potential role of HFD-induced alterations in GSK3β signaling and brain inflammation." (PMID 31920532, 2019). "Silencing of GSK3β in the DG therefore did not significantly impact locomotor activity and anxiety-like behavior." (PMID 26157370, 2015). "Similar changes in these tests have also been reported in GSK3β HET mice, whereas mutant mice lacking GSK3 inhibitory phosphorylation in both GSK3α and GSK3β isoforms display a general reduction of anxiety and depressive-like behaviours." (PMID 22826345, 2012). "Similarly, the pGSK-3βSer9/GSK-3β ratio remained unchanged in the AMYG suggesting that the interaction of FKBP5 and stress was not implicated in the increased anxiety in rTgFKBP5-ELS mice." (PMID 31167373, 2019). "Specifically, in relation to GSK-3, it has been shown that silencing GSK-3β in mice did not affect anxiety behavior, although other studies have shown that GSK-3 knockout mice revealed aberrant anxiety." (PMID 35574473, 2022).
pulmonary fibrosis (43 papers, 2012 to 2026). Chronic progressive interstitial lung disorder characterized by the replacement of the lung tissue by connective tissue, leading to progressive dyspnea, respiratory failure, or right heart failure. "The activity of GSK3β is closely associated with pulmonary fibrosis and lung aging, where the phosphorylation of GSK3β at Ser21 and Ser9 leads to decreased activity, thereby inhibiting pulmonary fibrosis and lung aging." (PMID 38671868, 2024). "The Wnt/GSK3β signaling pathway is closely associated with oxidative stress and lung fibrosis." (PMID 40377174, 2025). "Zhang and colleagues revealed that MSC-Exos attenuated the progression of silica-induced pulmonary fibrosis by suppressing expression of GSK3β and β-catenin which inhibited Wnt/β-catenin-driven fibrosis in the lungs." (PMID 38673961, 2024). "The PI3K/AKT/GSK-3β signaling pathway is involved in the development of pulmonary fibrosis and myocardial fibrosis." (PMID 38808258, 2024). "Bhlhe40 deficiency attenuates pulmonary fibrosis and repressed the PI3K/AKT/GSK-3β/β-catenin-integrated signaling pathway in mice and in A549 cells." (PMID 36304536, 2022). "GSK-3β inhibition likewise reversed the progression of pulmonary fibrosis in a preclinical model of pulmonary fibrosis." (PMID 35163509, 2022). "This study suggests that GSK3β is a potential target for treating pulmonary fibrosis and fibroproliferative lung diseases." (PMID 33672232, 2021). "In alveolar macrophages from pulmonary fibrosis patients and mice, GSK3β and the ubiquitin-editing enzyme A20 regulate C/EBPβ enzymatic activity and play a role in lung fibrosis." (PMID 33672232, 2021). "For instance, inhibition of GSK3β by 9ING41, a highly selective small-molecule inhibitor, was able to improve bleomycin-induced pulmonary fibrosis in mice." (PMID 33931588, 2021). "CXCL6 contributes to experimental pulmonary fibrosis induced with bleomycin in mice by PI3K/Akt/GSK-3β/Snail signaling." (PMID 32132577, 2020). "In summary, PFD not only alleviated pulmonary fibrosis of mice models caused by BLM, but also relieved TGF-β1-induced HLFs damage, which were mainly realized by regulating Wnt/GSK-3β/β-catenin and TGF-β1/Smad2/3 signaling pathways." (PMID 32448163, 2020). "The phosphorylation of AKT and GSK-3β were significantly increased in pulmonary fibrosis mice, and were dramatically inhibited by Hyp." (PMID 33192501, 2020). "In the present study, the p-AKT and p-GSK-3β were significantly elevated in pulmonary fibrosis mice, and these increased expressions were reversed after Hyp treatment." (PMID 33192501, 2020). "Several studies have shown that the inhibition of GSK-3β reduces the development of acute lung injury and inflammation and has a protective effect on lung fibrosis induced by BLM." (PMID 31075901, 2019). "GSK3A/GSK3B inhibition in bleomycin-exposed mice has been shown to reduce alveolitis, lung fibrosis, and alveolar cell apoptosis." (PMID 28440314, 2017). "Studies in animal models, as well as in human disease, have identified several components of the canonical WNT signaling pathway, including WNT2, FZD7, LRP6, β-CATENIN and GSK-3β which are overexpressed in idiopathic pulmonary fibrosis (IPF)." (PMID 22846383, 2012). "In silica dust-exposed rats with pulmonary fibrosis, reduced expression of total GSK3β protein and increased amounts of GSK3β with negative regulatory phosphorylation could be detected." (PMID 39125833, 2024). "The goal of this study was to see if N2FBR could reduce oxidative stress in BLM-induced lung fibrosis by triggering autophagy via the GSK-3β/mTOR pathway." (PMID 35903328, 2022). "Tribble’s homolog 3/glycogen synthase kinase-3β (TRIB3‒GSK-3β) interactions promote lung fibrosis and could be used as the potential therapeutic target." (PMID 36479199, 2022). "AhR could maintain GSK3β in an active form, thus suppressing epithelial-mesenchymal transition in lung cancer cells, which may be used to alleviate lung fibrosis." (PMID 35656117, 2022).
pulmonary fibrosis (continued). "Therefore, it stands to reason that GB1107 inhibited galectin-3 expression and attenuated the development of BLM-induced pulmonary fibrosis by suppressing the AKT/GSK3β/β-catenin singling pathway." (PMID 33771973, 2021). "PFD alleviated pulmonary fibrosis in vitro and in vivo through regulating Wnt/GSK-3β/β-catenin and TGF-β1/Smad2/3 signaling pathways, which might further improve the action mechanism of anti-fibrosis effect of PFD." (PMID 32448163, 2020). "Indeed, IL-17A promotes pulmonary fibrosis by attenuating autophagy via activating the PI3-kinase/GSK3b/Bcl-2 signaling cascade in lung epithelial cells." (PMID 28039485, 2017). "Thus, we studied the changes of the AKT/GSK3β signaling pathway in Blm-induced pulmonary fibrosis." (PMID 33192501, 2020). "Experimental results confirmed that MOL000332 (n-coumaroyltyramine) significantly mitigated pulmonary fibrosis by suppressing the protein expression levels of EGFR, HIF1A, and GSK3B." (PMID 41847136, 2026). "Interference with GSK-3β/OTUA (deubiquitinating enzyme) interaction in macrophages accelerates the degradation of the transcription factor CBP and attenuates pulmonary fibrosis." (PMID 39113708, 2024). "As demonstrated by Li and colleagues, by modulating the AKT/GSK3β signaling pathway in alveolar epithelial cells, MSC-Exo-derived miR-466f-3p suppressed SNAIL activity, prevented EMT and attenuated pulmonary fibrosis in irradiated mice." (PMID 38673961, 2024). "Serotonin not only promoted cardiac fibrosis and pulmonary fibrosis by activating the TGF-β signaling pathway but also enhanced β-catenin signaling by inhibiting GSK3β." (PMID 35656117, 2022). "Therefore, Hyp might inhibit EMT via the AKT/GSK3β pathway in pulmonary fibrosis." (PMID 33192501, 2020). "Several lines of evidence suggest that the radiation-induced EMT of AT2 cells is important in pulmonary fibrosis that is mediated by the TGF-β and ERK/glycogen synthase kinase 3β (GSK3β) pathways." (PMID 31959867, 2020). "For pulmonary fibrosis, Mai Men Dong Decoction-2 reduced epithelial–mesenchymal transition (EMT) by activation of TGF-β; Scutellariae Radix for EMT may be associated with its active component, baicalin, which inhibited extracellular regulated protein kinases (ERK)/Glycogen Synthase Kinase 3β(GSK3β)." (PMID 31616288, 2019). "Taken together, these findings suggest that ZBM may regulate the development of pulmonary fibrosis partly through the PI3K/AKT/MDM2 and PI3K/AKT/GSK3B signaling pathways." (PMID 36479180, 2022). "However, as suggested in a previous study on pulmonary fibrosis, there is a possibility that the TGF-β–induced cellular response in HTFs is regulated by GSK-3β–induced phosphorylation of a cAMP-responsive element-binding protein." (PMID 34940783, 2021). "In summary, we revealed that Hyp attenuated pulmonary fibrosis development in mice, and the potential mechanism might be due to inhibiting the Blm-induced inflammation, oxidative stress, and EMT via the AKT/GSK3β pathway." (PMID 33192501, 2020). "Furthermore, GSK3B is a serine/threonine kinase that can be activated by the AKT signaling cascade to regulate TGFβ and β-catenin signaling pathways to influence the development of pulmonary fibrosis." (PMID 36479180, 2022). "Our findings indicated that exosomal miR-466f-3p derived from mMSCs may possess anti-fibrotic properties and prevent radiation-induced EMT through inhibition of AKT/GSK3β via c-MET, providing a promising therapeutic modality for radiation-induced lung fibrosis." (PMID 35392967, 2022). "To further clarify whether the PI3K/AKT/GSK-3β/β-catenin signaling pathway participates in EMT in the BLM-induced PF murine model, we examined the effect of LY294002 and XAV-939, potent inhibitors of the PI3K/AKT and Wnt/β-catenin signaling pathways, respectively, on lung fibrosis induced by BLM." (PMID 35355710, 2022).
pulmonary fibrosis (continued). "This present study demonstrated that PFD inactivated BLM-induced GSK-3β/β-catenin pathway, suggesting that PFD could promote the degradation and reduce the accumulation of β-catenin through inhibiting the phosphorylation of GSK-3β S9, thereby relieving pulmonary fibrosis." (PMID 32448163, 2020).